MIR4489 (microRNA 4489)
Synonyms: hsa-mir-4489; mir-4489
Gene: MicroRNA gene on chromosome 11 (65,649,192 to 65,649,253, forward strand). Ensembl gene ENSG00000265874.
Homologues: Orthologues: chimpanzee MIR4489 (100% identical).